WT1 (WT1 transcription factor)
Diseases named in the same sentence as WT1 in open-access papers (continued):
Sharing a sentence is not in itself a finding about the gene and the disease.
kidney tumor (19 papers, 2004 to 2025). "Forty (27%) patients had a genetic predisposing factor for kidney tumors of which 10 with a WT1-related syndrome and 17 with a Beckwith-Wiedemann spectrum (BWSp)." (PMID 39966140, 2025). "This dual behaviour was also reported for other genes, such as Wilms’ tumour 1 (WT1); mutated WT1 led to the onset of kidney tumours, and its overexpression was detected in a subset of human cancers." (PMID 32888398, 2020). "For example, Wilms' tumour 1 (WT1) gene was initially discovered to behave as a tumour suppressor in kidney tumours." (PMID 39169452, 2024). "This emphasizes the significance of immunohistochemistry, particularly WT1 staining, incorrect diagnosis and differentiation of renal neoplasms." (PMID 38234938, 2023). "In adults, WT1 IHC staining addresses the differential diagnosis conundrum of subtyping renal tumors with a significant papillary component." (PMID 35453662, 2022). "This explains, at least in part, why several Wt1-Igf2 mice also developed not only renal tumors, but also extrarenal metastatic tumor lesions." (PMID 22875335, 2013). "In 35.6 % of Wt1-Igf2 mice, tumors were localized in the right kidney; in 24 %, in the left kidney, while 40.4 % of Wt1-Igf2 mice had bilateral kidney tumors." (PMID 22875335, 2013). "Renal tumors in Wt1-Igf2 mice accumulate 18F-FDG due to upregulation of Glut-1 and hexokinase activity." (PMID 22875335, 2013). "The level of Glut1 expression in renal tumors of Wt1-Igf2 mice was uniformly increased in the tumor cells, which contributes to the mechanism of 18F-FDG accumulation." (PMID 22875335, 2013). "Renal tumors were multifocal in 65.4 % of Wt1-Igf2 mice, while 34.6 % had a single detectable lesion only in one kidney." (PMID 22875335, 2013). "The current study also demonstrated the efficacy of dual contrast-enhanced CT (using co-administration i.v. and i.p. contrast) for detection and monitoring of renal tumors in Wt1-Igf2 mice." (PMID 22875335, 2013). "For the 9 renal tumors with overlapping morphologic features of MA and WT, WT1 and CD57 were positively expressed in both MA-like areas and epithelial WT-like areas, and Ki-67 indices of MA-like areas were 1-5%, less than that in epithelial WT-like areas (5-30%)." (PMID 36313688, 2022). "Renal tumors were identified in 54.3 % of Wt1-Igf2 mice between post-natal 50–100 days." (PMID 22875335, 2013). "DNA isolated from the lung metastasis had the same somatic homozygous WT1 deletion within the heterozygous 11p13 deletion and the uniparental disomies (UPD) in 1p, 3p, and 11p15 as the primary kidney tumor." (PMID 29542868, 2018). "In Wt1-Igf2 mice, the renal tumor signal intensity on non-enhanced T1 MR images was homogenous and only slightly lower than that of the adjacent cortico-medullary renal tissue, which did not provide sufficient tumor-to-adjacent kidney contrast." (PMID 22875335, 2013).
ovarian tumors (19 papers, 2011 to 2025). "This case highlights the diagnostic challenges of occult cervical adenocarcinoma mimicking PMP and underscores the critical role of immunohistochemical profiling (p16, PAX8, WT1) to differentiate metastatic from primary ovarian tumors." (PMID 41584594, 2025). "The samples were macroscopically normal in appearance, however positive staining for the ovarian tumour markers WT1 and Pax8 was observed in four of the 10 samples collected." (PMID 32716937, 2020). "In the female genital tract, WT1 expression is usually used to distinguish SOCs from other ovarian tumour types." (PMID 29662608, 2018). "WT1 IgG Ab titers in plasma were evaluated using ELISA in a total of 103 women with ovarian tumors (52 malignant OCs, 18 borderline tumors, 33 benign tumors)." (PMID 24715586, 2014). "The OV marker WT1 was also expressed in fewer A2780 cells as compared to Caov-4 (48% vs 85%), which suggests that A2780 could be a germ cell-derived ovarian tumor." (PMID 33926541, 2021). "In the tumoral ovary, WT1 is characteristic for the serous subtype of ovarian tumors." (PMID 33080944, 2020). "In this case, the ovarian tumor showed positivity for PAX8 and WT1." (PMID 31807285, 2019).
myeloid leukemia (18 papers, 2013 to 2026). A clonal proliferation of myeloid cells and their precursors in the bone marrow, peripheral blood, and spleen. "It was demonstrated that the WT1 expression level is associated with the cell proliferation rate and cell cycle phase of the K562 myeloid leukemia cells (the higher proliferation rate, the higher WT1 expression while the lower proliferation rate, the lower WT1 expression)." (PMID 33110919, 2020). "Aberrant DNA methylation mediated by mutations of TET2, WT1, DNMT1, DNMT3A, and DNMT3B genes is correlated to the pathogenesis of myeloid leukemia." (PMID 37375831, 2023). "Ex4a(+)WT1 isoform shows minor endogenous expression in myeloid leukemia/solid tumors cells, but during apoptosis, it becomes overexpressed, in spite of major isoform depletion." (PMID 35453662, 2022). "Based on the literature review, this study is the first report to show that WT1 can regulate the RNA expression of IL-2, IL-2RB, and IL-2RG in the myeloid leukemia cells." (PMID 33110919, 2020). "Overall, this study confirmed the oncogenic role of WT1 in myeloid leukemia and discovered the new target genes of WT1 which are likely involved in WT1-mediated leukemogenesis." (PMID 33110919, 2020). "With regard to apoptosis, specific silencing of WT1(+17AA) by siRNA induced apoptosis via activation of caspase-3 and caspase-9 in myeloid leukemia cells." (PMID 33110919, 2020). "Recently, another novel truncated WT1 isoform called Ex4a (+) WT1 isoform was observed in myeloid leukemia and solid tumor cells." (PMID 33110919, 2020). "Downregulation of WT1 gene resulted in reduced cell proliferation with G0/G1 arrest of the cell cycle in myeloid leukemia cells." (PMID 33110919, 2020). "The goals of this trial were to compare the effectiveness of a novel immune adjuvant in patients with myeloid leukemia as well as to offer further validation of the immunogenicity of the WT1 vaccine." (PMID 29344432, 2018). "To investigate the relationship between methylation of the CpG island in Intron 1 and WT1 expression, we evaluated 3 human myeloid leukemia cell lines—K562, U937, and HL60." (PMID 25794157, 2015). "We investigated the roles of hypoxia and epigenetics in the regulation of WT1 expression in myeloid leukemia cells." (PMID 25794157, 2015). "WT1 is a transcription factor expressed in hematopoietic stem cells and in most cases of myeloid leukemia." (PMID 25794157, 2015). "In clinical trials, PR1 was frequently used with the WT1 vaccine as a combination immunization strategy in myeloid leukemia patients." (PMID 23394714, 2013). "This hypothesis is also supported by the fact that WT1 is required to overcome apoptosis and potentiate proliferation in myeloid leukemia cells." (PMID 40493404, 2025). "Previous research found that WT1 inhibitors could impact cell cycle progression in myeloid leukemia." (PMID 37765274, 2023). "Moreover, suppression of WT1 by curcumin inhibited growth and induced G2/M arrest in myeloid leukemia cells." (PMID 33110919, 2020). "Similarly, besides miR-193a, miR-125a was identified to suppress WT1 expression via binding 3′UTR of WT1 in myeloid leukemia cells." (PMID 27821145, 2016). "However PASD1 has been one of the most frequently expressed CTA in myeloid leukaemia while WT1 has been found to be one of the most frequently expressed LAAs." (PMID 26492414, 2015). "Thus, the novel mechanism of regulation of WT1 expression uncovered in myeloid leukemia cell lines appears to be functional in primary AML samples as well." (PMID 25794157, 2015). "TCR-T cells specifically targeting Wilms’ tumor 1 (WT1; overexpressed in AML and MDS cells) demonstrated HLA-A*24:02-restricted cytotoxicity against WT1-expressing myeloid leukemias." (PMID 33718188, 2021). "Many cancers, including myeloid leukaemia express the cancer testis antigen (CTA) DDX43 (HAGE) and/or the oncogene Wilms’ tumour (WT1)." (PMID 34262856, 2021).
myeloid leukemia (continued). "Myeloid leukemia cell lines that express WT1 also express the lncRNA, while cell lines that do not express WT1 do not express the lncRNA." (PMID 25794157, 2015). "Ex4a(+)WT1 isoform was endogenously expressed as a minor isoform in myeloid leukemia and solid tumor cells and increased regardless of decrease in major WT1 isoforms during apoptosis, suggesting the dominant negative effects on anti-apoptotic function of major WT1 isoforms." (PMID 26090994, 2015).
myeloid malignancies (17 papers, 2015 to 2025). "Another clinical trial (NCT02550535) of autologous WT1-specific TCR-T cells was performed to assess treatment of high-risk myeloid malignancies, and it demonstrated strong efficacy with a good safety profile." (PMID 35356211, 2022). "Using these models, we identified a functional role for a WT1 mutation in myeloid neoplasms." (PMID 30450160, 2018). "The IDH1/2‐TET2‐WT1 pathway in myeloid malignancies explains the mutual exclusivity of IDH1/2, WT1, and TET2 mutations." (PMID 40599235, 2025). "Such dense clusters of hypermethylation included the translocated ABL1 promoter, the promoter regions of Wilms tumor 1 (WT1), a transcription factor overexpressed in myeloid malignancies, and the promoter of the ZNF577 gene that encodes a zinc finger protein." (PMID 29575763, 2018). "Indeed, at least one pathogenic mutation (WT1, FLT3-ITD, IDH2 or PTPN11 mutation) has been identified in all the reported myeloid tumors harboring NPM1::MLF1." (PMID 39443736, 2024). "Objective clinical responses have been documented in patients with myeloid malignancies following PR3 and WT1 peptide vaccination and with cellular-based WT1 vaccines." (PMID 25914882, 2015). "Among them, two had chromosomal abnormalities common to all myeloid neoplasms, whereas three had chromosomal abnormalities without WT1 mRNA expression." (PMID 39087180, 2024). "The vast majority of wild type mice have normal bone marrow, the majority of Flt3+/ITD mice develop a myeloid neoplasm (primarily MPN), the predominant phenotype in the Wt1+/R394W mice evaluated is MDS, and the majority of Flt3+/ITD/Wt1+/R394W mice develop an MDS/MPN." (PMID 30450160, 2018). "Repeated PR1 and WT1 peptide vaccination failed to induce sustained high-avidity, epitope-specific CD8+ T cells in myeloid malignancies." (PMID 35476127, 2022).
renal cell carcinoma (17 papers, 2007 to 2025). "Immunohistochemical profile of MC includes positivity for CK7, CAM5.2, EMA, CEA, GCDFP-15 (gross cystic disease fluid protein 15), RCC (renal cell carcinoma) antigen, WT1 (Wilms’ tumor protein), ER, PR, and AR." (PMID 34064849, 2021). "The regenerated WT1-specific CTLs had a strong therapeutic effect in orthotopic xenograft model using a renal cell carcinoma (RCC) cell line." (PMID 32259478, 2020). "Moreover, renal tissues gathered form IMN patients exhibited lower WT1 expressions than normal tissues that were excised form renal cell carcinoma patients (p < .05)." (PMID 31352863, 2019). "Mostly negative markers are CD34, Desmin, Wilms’ tumor protein (WT-1), smooth muscle antibody (SMA), MyoD1, S100, paired-box factor 8 (PAX8—regularly positive in renal cell carcinoma) and synaptophysin." (PMID 36143235, 2022). "Immunohistochemistry indicated FLI-1(+), CD99(+), Vimentin(+), CyclinD1(+), WT-1(+), EMA(+), Bcl2(-), Ki-67(+) 60%, CD56(-), CK(-), CD34(-), Desmin(-), and SMA(-), which suggested that renal clear cell sarcoma may not rule out renal cell carcinoma." (PMID 33859949, 2021).
colorectal cancer (16 papers, 1994 to 2024). A primary or metastatic malignant neoplasm that affects the colon or rectum. "Furthermore, the top 25 of most differentially expressed genes includes two genes that have previously been linked to colorectal cancer: Mmp25 and WT1." (PMID 25243059, 2014). "In colorectal cancer, studies have pointed out WTAP is also oncogenic and can promote the progression of colorectal cancer through the WTAP/WT1/TBL1 axis in the canonical Wnt signaling pathway." (PMID 35614935, 2022). "By far a number of targets have been reported for G-to-A RNA editing, such as HNRNPK in colorectal cancer and WT1 in cord blood samples." (PMID 34093668, 2021). "The present study indicated that DC vaccination targeting WT1 demonstrated the safety and immunogenicity as an adjuvant therapy in patients with resectable advanced colorectal cancer." (PMID 26690485, 2015). "Here, we investigated the safety and immunogenicity of DC vaccination targeting WT1 for patients with stage IV colorectal cancer as an adjuvant therapy following surgical resection and chemotherapy." (PMID 26690485, 2015). "We conducted a phase I study to investigate the safety and immunogenicity of Wilms’ tumor (WT1) class I/II peptides-pulsed dendritic cell DC vaccination for patients with advanced colorectal cancer." (PMID 26690485, 2015). "The strongest overlap between histopathological markers and the LDA based CUP classifications was observed for CUP predicited as ovary and colorectal cancers, where 4 and 3 samples expressed WT1 or CEA/CEACAM5, respectively." (PMID 25885340, 2015). "A phase I study of WT1 peptides-pulsed DC vaccination for patients with advanced colorectal cancer demonstrated the safety and immunogenicity as an adjuvant setting." (PMID 26690485, 2015). "Conversely, WT1 gene hypermethylation has been observed in cervical and colorectal cancer and has been shown to correlate with reduced WT1 expression in ovarian clear cell carcinoma." (PMID 21063414, 2010). "WTAP negatively regulate WT1.9 to promote tumorigenesis in colorectal cancer." (PMID 32742465, 2020). "DC vaccinations for colorectal cancer have been reported in a proportion of patients; however, safety and efficacy of DC vaccination therapy primed with WT1 peptides remains unclear." (PMID 26690485, 2015). "WT1 and HLA antigens may also provide a common target of DC vaccination therapy for heterogeneous colorectal cancer." (PMID 26690485, 2015). "Future studies evaluating DC vaccines pulsed with WT1-class I/II peptides may demonstrate the induction of WT1-CTLs primed against WT1 and HLA-class I/II-positive colorectal cancers." (PMID 26690485, 2015). "In addition, differential expression of genes linked to intestinal bowel disease (i.e. Ccr3, Ccl11 and Tnfr) and colorectal cancer development (i.e. Wt1 and Mmp25) was observed between males and females." (PMID 25243059, 2014). "However, the DC vaccination targeting WT1 as an adjuvant setting in the course of standard therapies may be feasible and well tolerable for advanced colorectal cancer." (PMID 26690485, 2015). "U-to-C was initially identified in the mRNA of Wilm’s tumor 1 (WT1) human transcript, while G-to-A was identified in the heterogeneous nuclear ribonucleoprotein K (hnRNP K) protein of colorectal cancer and surrounding tissues." (PMID 36290689, 2022). "A number of genes are commonly hypermethylated in colorectal cancer (CRC) including hMLH1, p16INK4a, p14ARF, RAR-β, APC, MGMT, cyclin A1, CDX1, MYOD1, COX-2 and WT-1." (PMID 19662090, 2009). "T cells from after vaccination stimulated by unirradiated DCs/auto-HCC lysed not only the HCC cells (HLA-A2+/A24-, WT1+, and CEA+) but also HLA class I-semimatched colorectal carcinoma cell line, COLP-2 (HLA-A2+/A24-) endogenously expressing WT1 and CEA." (PMID 18793383, 2008).
colorectal cancer (continued). "By contrast, no lysis of allogeneic colorectal carcinoma cell line, COLM-6 (HLA-A2- and A24-, WT1+ and CEA+) was observed, suggesting that HLA-A2 was, at least in part, the restriction element of CTL." (PMID 18793383, 2008).
rhabdomyosarcoma (15 papers, 2005 to 2025). A rare aggressive malignant mesenchymal neoplasm arising from skeletal muscle. "Our research group has recently shown that WT1 is a marker that can be expressed at the cytoplasmic level in childhood fibrosarcoma, juvenile-type fibromatoses, and rhabdomyosarcoma." (PMID 33445443, 2021). "Only 2 out of 10 cases of high grade rhabdomyosarcoma with strong WT1 expression died as a result of the disease, while all two patients of high grade rhabdomyosarcoma with weak WT1 expression died of disease." (PMID 25026998, 2014). "Most rhabdomyosarcomas and malignant peripheral nerve sheath tumors showed WT1 expression (91.7% and 71.4%, respectively; P = 0.005)." (PMID 25026998, 2014). "Ohta el al. reported that WT1 peptide vaccination was effective in a pediatric patient with metastatic alveolar rhabdomyosarcoma who showed poor response to chemotherapy, and the patient had no adverse effects other than skin erythema." (PMID 25026998, 2014). "It seems reasonable that WT1 cancer immunotherapy should be considered, especially in rhabdomyosarcoma and MPNST." (PMID 25026998, 2014). "Cytoplasmic staining of WT1 has been previously reported in rhabdomyosarcoma samples." (PMID 24810959, 2014). "Rhabdomyosarcoma was strongly correlated with WT1 expression (91.7%, P = 0.005)." (PMID 25026998, 2014). "Our results revealed that rhabdomyosarcoma and MPNST showed frequent WT1 expression (91.7% and 71.4%, respectively)." (PMID 25026998, 2014). "This study demonstrates that various types of STS shows positive cytoplasmic immunostaining for WT1 and STS patients should be considered candidates for WT1 peptide-based immunotherapy, particularly in cases of rhabdomyosarcoma and MPNST." (PMID 25026998, 2014). "Rhabdomyosarcomas and MPNST showed WT1 expression in a high proportion." (PMID 25026998, 2014). "Among other small round cell tumors, most of cases of rhabdomyosarcomas and neuroblastomas do not disclose nuclear WT1 staining." (PMID 15777480, 2005).